KDM2A (lysine demethylase 2A)
Diseases named in the same sentence as KDM2A in open-access papers (continued):
Sharing a sentence is not in itself a finding about the gene and the disease.
tumor (continued). "Therefore, we investigated the effect of KDM2A on tumor angiogenesis in vitro and in vivo." (PMID 27029061, 2016). "RT-qPCR results documented that lncRNA HOXA-AS2, KDM2A, and JAG1 expression was diminished, while that of miR-302a was augmented in tumor tissues of BALB/c mice silencing lncRNA HOXA-AS2." (PMID 35181676, 2022). "In this article, we report circFOXO3 promotes tumor growth and invasion of OSCC by targeting miR‐214 which specifically degrades the lysine demethylase 2A (KDM2A)." (PMID 34117688, 2022). "To validate the dependency of tumor cells on CSNK1A1, KDM2A, and LTB4R2 in vitro, we generated the knockout (KO) of each gene by independently introducing two sgRNAs in two AD cell lines, NCI-H23 and A549." (PMID 34298691, 2021). "As such, the mammalian lysine-specific demethylase 2 (KDM2) homologs, KDM2A and KDM2B, are either oncogenic or tumor suppressive depending on specific pathological contexts." (PMID 30233643, 2018). "A recent study revealed that KDM2A paralog specifically interacts with nucleosome acidic patch and facilitates dynamic nucleosomal DNA unwrapping and histone charge shielding that induce the H3K36 sequence for demethylation in tumor cells." (PMID 40303308, 2025). "In NSCLC, it has been reported that DUSP3 expression is epigenetically repressed by the histone H3 lysine 36 demethylase KDM2A (also called FBXL11 and JHDM1A), which is frequently overexpressed in NSCLC tumours and cell lines, and the high level of expression of which correlates with poor prognosis." (PMID 40943262, 2025). "Previous study showed that KDM2A and PFKFB3 promoted angiogenesis in various tumor cells." (PMID 34079757, 2021). "Co-injection with the normal RMF-EG fibroblasts promoted tumour growth while co-injection with the KDM2A-depleted RMF-EG cells did not." (PMID 33024266, 2021). "KDM2A was found highly dysregulated in 54 NSCLC cell lines according to Affymetrix microarray gene expression data, and its mRNA and protein levels are significantly higher in primary NSCLC tumor samples than in adjacent normal lung tissues." (PMID 30002791, 2018). "However, DNA methylation at cg11637544 in the first exon of KDM2A and at cg26662347 in the 200-kb TSS region of KDM1A elevates corresponding expression in tumor tissues." (PMID 29619118, 2018). "In this study we show that the microRNA hsa-miR-137 (miR137) tumor suppressor regulates expression of an extended network of transcriptional coregulators including KDM1A/LSD1/AOF1, KDM2A/JHDM1A/FBXL11, KDM4A/JMJD2A, KDM5B JARID1B/PLU1, KDM7A/JHDM1D/PHF8, MED1/TRAP220/DRIP205 and NCoA2/SRC2/TIF2." (PMID 26461474, 2015). "Furthermore, knockdown of KDM2A abolished the promotion of breast tumor growth by CAFs in vivo, reduced PD-L1 expression in the stroma, and inhibited NOTCH signaling, which can interfere with tumor angiogenesis." (PMID 36291773, 2022). "However, upregulated JAG1 was observed in tumor tissues of BALB/c mice treated with oe-JAG1 along with no significant alterations in the lncRNA HOXA-AS2, KDM2A and miR-302a expression in the presence of sh-lncRNA HOXA-AS2." (PMID 35181676, 2022).
metabolic disorders (3 papers, 2023 to 2025). "Therefore, we propose that the Kdm2a gene plays a crucial role in the kidney function, leading to metabolic disorders and mild inflammation." (PMID 39940999, 2025). "Collectively, these data support the notion that liver-specific KDM2A deficiency may enhance inflammation in the liver, potentially through NF-κB activation, and lead to liver dysfunction, thus suggesting that KDM2A may be a promising therapeutic target for liver-related metabolic diseases." (PMID 37892137, 2023).
cardiovascular disease (2 papers, 2022 to 2025). "Although, these studies suggest that KDM2A is an important TR, no study has revealed a potential association of KDM2A in cardiovascular disease." (PMID 40303308, 2025).
neurodegenerative disease (1 paper, 2024). A disorder of the central nervous system characterized by gradual and progressive loss of neural tissue and neurologic function. "Regarding neurodegenerative diseases, the HDMs KDM2A and KDM2B were shown to play a role in AD." (PMID 39765675, 2024).
neurodevelopmental disorder (1 paper, 2026). A behavioral and cognitive disorder with onset during the developmental period that involves impaired or aberrant development of intellectual, motor, or social functions. "Combining our genetic, phenotypic, and functional findings, we establish de novo variants in KDM2A as causative for a syndromic neurodevelopmental disorder." (PMID 41468891, 2026).
KDM2A also shares sentences with these, for which no sentence is quoted: ovarian carcinoma (4 papers); Hepatic steatosis (2); Hyperglycemia (2); meningioma (2); non-small cell lung carcinoma (2); acute myelogenous leukemia (1); adrenoleukodystrophy (1); amyotrophic lateral sclerosis (1); bladder tumors (1); cervical tumor (1); developmental epileptic encephalopathy (1); endometriosis (1); epilepsy (1); fibromyxoid tumor (1); frontotemporal dementia (1); genetic disorders (1); glioblastoma (1); Infertility (1); Intellectual disability (1); invasive breast carcinoma (1); lung adenocarcinoma (1); metachromatic leukodystrophy (1); microcephaly (1); mitral valve prolapse (1); nasopharyngeal carcinoma (1); oligospermia (1); oral squamous cell carcinoma (1); papillary thyroid carcinoma (1); rhabdomyosarcoma (1); squamous cell carcinoma (1).
A further 3 diseases each share a sentence with KDM2A in 1 paper.